TUBA1B (tubulin alpha 1b)
Description:
Tubulin is the major constituent of microtubules, protein filaments consisting of alpha- and beta-tubulin heterodimers. Microtubules grow by the addition of GTP-tubulin dimers to the microtubule end, where a stabilizing cap forms. Below the cap, tubulin dimers are in GDP-bound state, owing to GTPase activity of alpha-tubulin.
Synonyms: K-ALPHA-1
Tractability: Small molecule: an approved drug acts on it; a structure with a bound ligand is known; a high-quality ligand is known; it belongs to a druggable protein family. PROTAC: UniProt records ubiquitination sites on it; ubiquitination databases record sites on it; a small molecule that binds it is known. Other modalities: an approved drug acts on it.
Target class: Structural protein
Gene: Protein-coding gene on chromosome 12 (49,127,782 to 49,131,397, reverse strand). Ensembl gene ENSG00000123416.
Subcellular location: Cytoplasm, cytoskeleton
Subcellular location (Human Protein Atlas): Microtubules; Primary cilium
Pathways (Reactome):
Cell Cycle: EML4 and NUDC in mitotic spindle formation; Mitotic Prometaphase; Recruitment of NuMA to mitotic centrosomes; Resolution of Sister Chromatid Cohesion; Sealing of the nuclear envelope (NE) by ESCRT-III; Separation of Sister Chromatids; The role of GTSE1 in G2/M progression after G2 checkpoint
Vesicle-mediated transport: COPI-dependent Golgi-to-ER retrograde traffic; COPI-independent Golgi-to-ER retrograde traffic; COPI-mediated anterograde transport; Gap junction assembly; Microtubule-dependent trafficking of connexons from Golgi to the plasma membrane; Translocation of SLC2A4 (GLUT4) to the plasma membrane
Signal Transduction: Hedgehog 'off' state; RHO GTPases Activate Formins; RHO GTPases activate IQGAPs; RHOH GTPase cycle
Metabolism of proteins: Carboxyterminal post-translational modifications of tubulin; Formation of tubulin folding intermediates by CCT/TriC; Post-chaperonin tubulin folding pathway
Immune System: MHC class II antigen presentation; PKR-mediated signaling
Neuronal System: Activation of AMPK downstream of NMDARs; Assembly and cell surface presentation of NMDA receptors
Organelle biogenesis and maintenance: Cargo trafficking to the periciliary membrane; Intraflagellar transport
Autophagy: Aggrephagy
Cellular responses to stimuli: HSP90 chaperone cycle for steroid hormone receptors (SHR) in the presence of ligand
Developmental Biology: Recycling pathway of L1
Disease: HCMV Early Events
Hemostasis: Kinesins
Gene Ontology:
Molecular function: double-stranded RNA binding; GTP binding; GTPase activity; protein binding; structural constituent of cytoskeleton; ubiquitin protein ligase binding; structural molecule activity
Biological process: microtubule cytoskeleton organization; cell division; cytoskeleton-dependent intracellular transport; microtubule-based process; mitotic cell cycle; neuron differentiation
Cellular component: cilium; microtubule; microtubule cytoskeleton; cytoplasmic microtubule; cytoskeleton
Genetic constraint (gnomAD): Loss-of-function variants: 1 observed, 36.64 expected, observed/expected ratio (o/e) 0.0273, 90% interval 0.009 to 0.13. The upper end of that interval is the gene's LOEUF score, 0.13, which puts it in group 1 of 6, group 1 being the genes least tolerant of losing a copy. Missense variants: 54 observed, 606.91 expected, observed/expected ratio (o/e) 0.089, 90% interval 0.071 to 0.11. Synonymous variants: 197 observed, 210.86 expected, observed/expected ratio (o/e) 0.93, 90% interval 0.83 to 1.05.
Homologues: Orthologues: chimpanzee TUBA1B (100% identical), guinea pig TUBA1B (100% identical), mouse Tuba1b (100% identical), rat Tuba1b (100% identical), tropical clawed frog tubal3 (100% identical), dog TUBA1B (99% identical), pig TUBA1B (99% identical), Drosophila melanogaster alphaTub84B (96% identical), Drosophila melanogaster alphaTub84D (96% identical). Paralogues in human: TUBA1A (99% identical), TUBA1C (98% identical), TUBA3C (97% identical), TUBA3D (97% identical), TUBA4A (96% identical), TUBA3E (96% identical), TUBA8 (90% identical), TUBAL3 (73% identical), TUBB4B (43% identical), TUBB4A (43% identical), TUBB3 (43% identical), TUBB (43% identical), and 11 more.
Diseases named in the same sentence as TUBA1B in open-access papers:
TUBA1B is named in the same sentence as 58 diseases in open-access papers, as found by Europe PMC text mining. Sharing a sentence is not in itself a finding about the gene and the disease. The quoted sentences say what the papers report.
hepatocellular carcinoma (10 papers, 2020 to 2025). A malignant tumor that arises from hepatocytes. "Although research on TUBA1B’s role in human cancers is limited, some studies have linked it to poor prognosis and chemotherapy resistance in hepatocellular carcinoma and disease progression in Wilms’ tumor." (PMID 39968182, 2025). "In hepatocellular carcinoma, elevated TUBA1B expression has been associated with a superior response to ICI therapy." (PMID 39578878, 2024). "In addition, increased expression of TUBA1B in patients with hepatocellular carcinoma was associated with poor overall survival and tolerability of paclitaxel." (PMID 32908931, 2020). "In hepatocellular carcinomas, increased TUBA1B expression levels indicated a poor prognosis and resistance to chemotherapy." (PMID 40453362, 2024). "TubA1B expression was found to be upregulated in hepatocellular carcinoma (HCC) tumor tissues and correlated with poor overall survival and resistance to paclitaxel in HCC patients." (PMID 35008169, 2021). "TUBA1B was found to be upregulated in the hepatocellular carcinoma tissues and the proliferating hepatocellular carcinoma cells." (PMID 32908931, 2020). "Furthermore, TUBA1B has been shown to mediate the infiltration of several immune cells in hepatocellular carcinoma and colorectal cancer." (PMID 40171266, 2025). "In addition, TUBA1B has been shown to mediate the infiltration of several immune cells in hepatocellular carcinoma, including CD274 and CTLA4." (PMID 36140469, 2022). "The higher expression of TUBA1B and poor prognosis were reported in hepatocellular carcinoma." (PMID 34350460, 2021). "For example, TUBA1B has been studied in hepatocellular carcinoma and mantle cell lymphoma." (PMID 32908931, 2020). "TUBA1B has also been reported in hepatocellular carcinoma and mantle cell lymphoma." (PMID 32908931, 2020). "TUBA1B was found upregulated in the hepatocellular carcinoma (HCC) and mantle cell lymphoma, also its increased expression was associated with poor survival." (PMID 35622738, 2022). "Further comparative analysis of TUBA1B expression levels across tumor tissues showed that glioblastoma multiforme (GBM) had the highest expression, while hepatocellular carcinoma (LIHC) exhibited the lowest." (PMID 39968182, 2025). "Raw data was extracted from TCGA and GEO databases, and then HCCDB, TIMER, HPA, and GEPIA websites, as well as R software, were used to perform bioinformatics analysis to investigate the potential of TUBA1B as a prognostic and immunotherapeutic marker for hepatocellular carcinoma (HCC)." (PMID 35453905, 2022).
breast carcinoma (8 papers, 2020 to 2025). "For the first time, we identified a new TAM subtype capable of proliferation and expansion in breast cancer-TUBA1B+ TAMs playing a crucial role in TAMs diversity and tumor progression." (PMID 39232806, 2024). "Adam8 has been considered an important participant in invasive malignant tumors, including breast cancer, pancreatic cancer, and brain cancer, and Tuba1b, as a key regulator of osteosarcoma and is related to the lifetime of colon adenocarcinoma." (PMID 40303139, 2024). "Our TCGA analysis confirmed this as significant upregulation of TUBA1B genes in breast cancer tissues, suggesting its potential oncogenic role." (PMID 35622738, 2022). "Inconsistent, our analysis showed promoter hypomethylation of the TUBA1B gene in breast cancer tissues confirming its epigenetic regulation." (PMID 35622738, 2022). "Very recently, a pseudogene-derived upregulation of the TUBA1B gene was also reported in human breast cancer samples." (PMID 35622738, 2022). "For the first time in breast cancer, we identified TUBA1B+ TAMs with proliferative and expansional ability, which may serve as precursors for other TAM subtypes." (PMID 39232806, 2024). "In this study, for the first time, we report five oncogenes (TUBA1B, SLC2A1, PGK1, CCND1, and NCAPD2) and two tumor suppressors’ genes (RPLP2, RPL37) as novel therapeutic targets in breast cancer." (PMID 35622738, 2022). "For the first time in this study, we used a comprehensive in silico approach and identified five proto-oncogenes (TUBA1B, SLC2A1, PGK1, CCND1, and NCAPD2) and two tumor suppressor genes (RPLP2, RPL37) as novel therapeutic targets against breast cancer." (PMID 35622738, 2022). "TUBA1B, SLC2A1, PGK1, CCND1, and NCAPD2 have been overexpressed in breast cancer tissues and their promoter region was hypomethylated (The graph on top shows gene expression and the graph at the bottom shows methylation beta value)." (PMID 35622738, 2022). "TUBA1B+ TAMs, C1QC+ TAMs and VCAN+ TAMs were more prevalent in HER2+ breast cancer, whereas IL1B+ TAMs, SLC40A1+ TAMs and APOC1+ TAMs were more dominant in ER+ breast cancer, which illustrates the heterogeneity of TAM subtypes in various molecular subtypes of breast cancer." (PMID 39232806, 2024).
colon adenocarcinoma (5 papers, 2022 to 2025). "TUBA1B enables double-stranded RNA binding activity and ubiquitin protein ligase binding activity, and low TUBA1B expression has been associated with adverse effects on the overall survival of patients with colon adenocarcinoma." (PMID 39337373, 2024). "In addition, low TUBA1B expression has been associated with adverse effects on the overall survival (OS) of patients with colon adenocarcinoma (COAD), leading to CD8 + T cell depletion and impacting COAD patients' response to immunotherapy." (PMID 38589634, 2024). "TUBA1B may play crucial roles in promoting tumor progression, including colon adenocarcinoma, osteosarcomas, liver hepatocellular carcinoma, and renal cell carcinoma." (PMID 40171266, 2025). "Moreover, it was revealed that TUBA1B expression was related to the overall survival (OS) of colon adenocarcinoma (COAD) patients and contributes to the exhaustion of the CD8+ T cell." (PMID 35453905, 2022).
colorectal cancer (5 papers, 2017 to 2025). A primary or metastatic malignant neoplasm that affects the colon or rectum. "However, TUBA1B, a critical gene in postmenopausal osteoporosis, has also been linked to BMI in children’s muscles and the overall survival of colorectal cancer patients." (PMID 37547318, 2023). "Additionally, the suppression of TUBA1B in colorectal cancer significantly reduced cancer cell viability and inhibited tumour cell proliferation." (PMID 40974979, 2025).
glioma (5 papers, 2021 to 2025). A benign or malignant brain and spinal cord tumor that arises from glial cells (astrocytes, oligodendrocytes, ependymal cells). "Based on these findings, the nomogram is more accurate in predicting glioma patient survival than any single diagnostic feature, highlighting the potential of TUBA1B as a valuable prognostic biomarker." (PMID 40094001, 2025). "Our analysis of CGGA data confirmed the significant association between TUBA1B expression and poor prognosis in glioma patients." (PMID 40094001, 2025). "TUBA1B is highly expressed in specific cell populations, such as oligodendrocytes and glioma cells, and is associated with extensive communication networks, indicating its potential collaborative regulatory role in gliomas." (PMID 40094001, 2025). "In conclusion, TUBA1B regulates cell cycle progression and associated pathways, significantly affecting glioma cell proliferation, migration, and invasion." (PMID 40094001, 2025). "The study demonstrates that high TUBA1B expression is closely associated with glioma malignancy and poor prognosis, making it a potential therapeutic target." (PMID 40094001, 2025). "Among TME-infiltrating male MG, we found cluster MG8 characterized by a high expression of genes encoding proliferation-related proteins (Stmn1, Tubb5, Tuba1b, Cdk1, and Top2a), which is consistent with the observed proliferation of MG within glioma TME, as previously reported." (PMID 33608526, 2021). "Furthermore, TUBA1B expression levels could be used to stratify glioma patients based on their risk of progression, enabling more personalized treatment approaches." (PMID 40094001, 2025). "For TUBA1B-high-expressing Glioma cells, signal output was primarily through the PTN, ANNEXIN, VEGF, PROS, and BMP pathways, while signal input occurred via the PTN, SPP1, and MK pathways." (PMID 40094001, 2025). "Collectively, these findings underscore the vital role of TUBA1B in the occurrence, development, and treatment of gliomas, suggesting its potential as a clinical target." (PMID 40094001, 2025). "In vitro functional experiments further confirmed that TUBA1B promotes the proliferation, migration, and invasion of glioma cells and is related to dynamic changes in the immune microenvironment." (PMID 40094001, 2025). "Machine learning analysis indicates that TUBA1B is a key driver of glioma progression, with high expression correlating with poor prognosis and aggressive tumor behavior." (PMID 40094001, 2025). "TUBA1B has shown promising potential as a prognostic biomarker for glioma patients, with higher expression levels correlating with poor survival outcomes." (PMID 40094001, 2025). "In summary, this study delineates the complex mechanisms of TUBA1B in gliomas, offering a new perspective on the role of aggrephagy in malignant tumors." (PMID 40094001, 2025). "Moreover, as TUBA1B is implicated in modulating the tumor microenvironment, future research could explore the synergy between TUBA1B inhibition and immunotherapy, which might enhance the immune response against glioma." (PMID 40094001, 2025). "In contrast, TUBA1B-low-expressing Glioma cells mainly transmitted signals through the PTN pathway and received signals via the PTN, MK, EGF, and CALCR pathways." (PMID 40094001, 2025). "Both TUBA1B-high and TUBA1B-low Glioma cell groups were found to be involved in pathways related to starch and sucrose metabolism, propionate metabolism, oxidative phosphorylation, fatty acid degradation, and butyrate metabolism." (PMID 40094001, 2025). "To explore the impact of TUBA1B expression on tumor stemness in glioma, we conducted a Spearman correlation analysis." (PMID 40094001, 2025). "Our in vitro experiments further validated the multifaceted role of TUBA1B in promoting cell proliferation and migration and inhibiting autophagy and apoptosis in gliomas, suggesting its potential as a therapeutic target." (PMID 40094001, 2025).
glioma (continued). "Analysis of TUBA1B expression across different cell groups revealed that TUBA1B was predominantly expressed in Oligodendrocytes, Macrophages, Glioma cells, and Pericytes." (PMID 40094001, 2025). "TUBA1B was shown to influence glioma cell proliferation, migration, invasion, and autophagy, impacting tumor progression and treatment response through intercellular communication and metabolic pathways." (PMID 40094001, 2025). "As expected, TUBA1B-high-expressing Oligodendrocytes, Macrophages, and Glioma cells displayed strong communication abilities." (PMID 40094001, 2025). "The results indicate that TUBA1B potentially modulates tumor biology in human gliomas by affecting the immune microenvironment, especially through its impact on fibroblast infiltration and diverse immune cell types." (PMID 40094001, 2025). "Through clustering analysis of The Cancer Genome Atlas (TCGA) dataset, we found that a high level of TUBA1B expression in gliomas indicates a poor prognosis and a rapid progression of the disease." (PMID 40094001, 2025). "Statistical analysis indicated that the total fluorescence intensity of the tumor in the TUBA1B knockdown group was significantly lower than that in the control group, further proving the oncogenic role of TUBA1B in glioma." (PMID 40094001, 2025). "To facilitate the clinical application of TUBA1B as a prognostic marker, we constructed a nomogram incorporating various clinicopathological factors, including TUBA1B expression, to better predict overall survival rates for glioma patients." (PMID 40094001, 2025). "In this study, we explore the role of aggrephagy and its key gene, TUBA1B, in glioma, uncovering its multiple impacts on the tumor microenvironment." (PMID 40094001, 2025). "We divided the TCGA database into high and low TUBA1B expression groups based on the median expression level in order to examine TUBA1B’s role in gliomas." (PMID 40094001, 2025). "Furthermore, high TUBA1B expression is correlated with enhanced tumor stemness and decreased sensitivity to immunotherapy in glioma." (PMID 40094001, 2025). "However, the addition of the cell cycle activator Cyclin D1 partially restored the inhibitory effect of TUBA1B knockdown on cell migration and invasion, further validating that TUBA1B regulates glioma cell behavior through the cell cycle." (PMID 40094001, 2025). "Our findings support these observations and suggest that TUBA1B’s role in glioma may be multifaceted, affecting not only tumor growth but also the tumor microenvironment, potentially enhancing immune evasion." (PMID 40094001, 2025). "Future in-depth experimental validation of the functions of TUBA1B, as well as its application in diverse clinical conditions, may propel the development of precision medicine and targeted therapies in gliomas." (PMID 40094001, 2025). "Furthermore, the retrospective nature of the data used in our analysis may limit the generalizability of our findings, and prospective studies are necessary to validate the clinical relevance of TUBA1B in glioma patients." (PMID 40094001, 2025). "Notably, TUBA1B expression was found to correlate with a shift in immune cell composition, particularly in terms of macrophage infiltration, which may contribute to immune evasion mechanisms in gliomas." (PMID 40094001, 2025). "We identified TUBA1B and TUBA1C as the most significant prognostic genes in glioma by integrating results from random forest, univariate, and multivariate Cox regression analyses, highlighting their high weights." (PMID 40094001, 2025). "Specifically, in Glioma cells, regardless of TUBA1B expression levels, these cells mainly interacted with Macrophages, Glioma cells, and Pericytes." (PMID 40094001, 2025). "This analysis across multiple cancers revealed significant correlations between TUBA1B expression and promoter methylation in nine tumor types, with ovarian cancer (OV) showing the highest positive and lower-grade gliomas (LGG) the highest negative correlation." (PMID 39968182, 2025).
acute myeloid leukemia (3 papers, 2020 to 2025). Acute myeloid leukemia (AML) is a group of neoplasms arising from precursor cells committed to the myeloid cell-line differentiation. "Interestingly, acute myelogenous leukemia (LAML) exhibited lower TUBA1B expression, distinguishing it from other cancer types." (PMID 39968182, 2025).
osteosarcoma (3 papers, 2019 to 2025). A usually aggressive malignant bone-forming mesenchymal neoplasm, predominantly affecting adolescents and young adults. "And there were 38 endogenous genes (including ARF1, HSP90AB1, and TUBA1B), 53 TFs (including E2F1, NFKB1, and EGR1), and 858 ncRNAs (including MALAT1, miR-590-3p, and TUG1) were considered as key regulators of osteosarcoma through a series of function enrichment analysis and network analysis." (PMID 30936265, 2019).
escherichia coli infection (2 papers, 2020 to 2021). Infection with the organism Escherichia Coli. "The coexpressed genes of TUBA1B were enriched in the pathway of DNA replication, mismatch repair, cell cycle, pathogenic Escherichia coli infection, and spliceosome." (PMID 32908931, 2020).